EXT2 (exostosin glycosyltransferase 2)
Diseases named in the same sentence as EXT2 in open-access papers (continued):
Sharing a sentence is not in itself a finding about the gene and the disease.
type 2 diabetes (8 papers, 2007 to 2024). "In humans, genetic variation in the EXT2 gene, which encodes for exostosin glycosyltransferase 2, an enzyme involved in the heparan sulfate biosynthesis, is associated with increased risk for Type 2 diabetes and impaired glucose clearance." (PMID 39290144, 2024). "Among our samples, we found three genetic variants (rs9300039, rs11037909 in EXT2 and rs3740878 in EXT2) that potentially increase the risk for type 2 diabetes." (PMID 35899193, 2022). "EXT2 encodes a protein involved in heparin sulfate biosynthesis, and associates with hereditary multiple exostoses and type 2 diabetes." (PMID 26322636, 2015). "Interestingly, common single nucleotide polymorphisms (SNPs) in EXT2 were associated with increased risk for the development of type 2 diabetes mellitus (DM2)." (PMID 25541963, 2014). "Interestingly, HS plays a role in pancreas development and beta-cell function, and genetic variations in EXT2 are associated with an increased risk for type 2 diabetes mellitus." (PMID 25541963, 2014). "We identified fourteen type 2 diabetes-associated genes discovered by the first waves of GWAS for which there was little prior evidence of their potential role in diabetes (Adam30, Adamts9, Camk1d, Cdc123, Cdkal1, Cdkn2a, Cdkn2b, Ext2, Hhex, Ide, Jazf1, Lgr5, Thada and Tspan8)." (PMID 23442068, 2013). "Nemr and colleagues could not replicate association of EXT2 genetic variants with the risk of type 2 diabetes in a population of Lebanese Arabs." (PMID 27877192, 2016). "Very recently, genetic variations within four novel genetic loci (SLC30A8, HHEX, EXT2, and LOC387761) were reported to be more frequent in subjects with type 2 diabetes than in healthy controls." (PMID 17786204, 2007).
exostoses (6 papers, 2014 to 2022). "EXT2 gene polymorphism is associated with humans with exostosis (or osteoma, benign growth of new bone on top of the existing bone)." (PMID 34327051, 2021). "Considering that dominant mutations in EXT1 and EXT2 genes cause hereditary multiple exostoses and the EXTL1 gene is expressed at very low levels in brain cells, EXTL2 and EXTL3 represent the most promising candidates in this pathway for SRT." (PMID 32121121, 2020). "Such a situation is likely to elicit NMD and the reduction of transcript levels leading to haploinsufficiency of EXT2, which would contribute for the exostosis phenotype in patients carrying the c.743+1 G>A mutation." (PMID 24728384, 2014). "Hereditary multiple exostoses is a relatively frequent autosomal dominant bone disorder resulting from heterozygous inactivating mutations of EXT1 and EXT2 genes." (PMID 24532482, 2014). "To the best of our knowledge, no patients, other than patient 2 with exostosis, have been reported until now, and we did not analyse patient 2 for the presence of an additional genetic defect, in particular for EXT1 or EXT2 mutations." (PMID 31555217, 2019).
glioblastoma (5 papers, 2017 to 2025). The most malignant astrocytic tumor (WHO grade IV). "The identification of EXT2 as a regulator of ferroptosis has significant therapeutic implications for glioblastoma treatment." (PMID 41008983, 2025). "EXT2 depletion in glioblastoma cells results in reduced viability, enhanced radiosensitivity, and increased susceptibility to ferroptosis." (PMID 41008983, 2025). "Recent investigations have identified EXT2 as a novel regulator of ferroptosis sensitivity in glioblastoma owing to its unexpected effects on cellular metabolism." (PMID 41008983, 2025). "In conclusion, this preliminary study pointed out for the first time, to the best of our knowledge, the potential role of CDK4 and EXT2 in the peritumoural brain zone of glioblastoma as driver genes forwarding the malignant transformation of this area." (PMID 36769158, 2023). "Both regions include genes of interest for glioblastoma, such as EXT2, SSTR5, SSTR5-AS1, C1QTNF8 and CACNA1H." (PMID 34827152, 2021). "For example, the expression level of the EXT2 gene is increased in glioblastoma; C1QTNF8 promotes temozolomide resistance; CACNA1H promotes GBM cell proliferation and migration." (PMID 34827152, 2021).
Intellectual disability (5 papers, 2013 to 2022). "Clinical cardinal features of PSS syndrome are multiple exostoses (due to the EXT2 involvement), biparietal foramina (due to the ALX4 involvement), intellectual disability, and craniofacial anomalies (due to the PHF21A involvement)." (PMID 36555772, 2022). "Current literature implies a minimal region with haploinsufficiency of three genes, ALX4 (parietal foramina), EXT2 (multiple exostoses), and PHF21A (craniofacial anomalies, and intellectual disability)." (PMID 33126574, 2020).
Enchondromatosis (4 papers, 2011 to 2024). Enchondromatosis is a rare primary bone dysplasia disorder characterized by the development of multiple mainly unilateral or asymmetrically distributed enchondromas throughout the metaphyses of the long bones. "Functional mutations in the exostosin genes (EXT1 and EXT2) are reported to affect the hedgehog signalling pathways leading to multiple enchondromatosis." (PMID 36676722, 2022). "Unlike enchondromatosis, EXT-1 and EXT-2 mutation (exostosin protein) is not observed in metachondromatosis." (PMID 39027184, 2024).
osteosarcoma (4 papers, 2013 to 2023). A usually aggressive malignant bone-forming mesenchymal neoplasm, predominantly affecting adolescents and young adults. "In humans, mutations in either of the exostosin genes EXT1 and EXT2 lead to osteosarcomas or multiple exostoses." (PMID 28068429, 2017). "The osteosarcoma sample presented mutations involving ATRX, ERCC5, and COL1A1, while the leiomyosarcoma case showed EXT2, DNM2, and PSIP1 alterations." (PMID 36673024, 2023). "Additionally, clinically relevant germline variants were detected in four cancer-associated genes, including an SBDS splice-site mutation (c.258 + 2T > C) in a rhabdomyosarcoma, BARD1 p.E652fs*69 in a neuroblastoma, EP300 p.A2259fs*20, and EXT2 p.W414* in two osteosarcoma patients." (PMID 35585047, 2022).
Autoimmunity (3 papers, 2021 to 2025). The occurrence of an immune reaction against the organism's own cells or tissues. "These patients were carefully screened and followed up, and none was found to have a tumor, suggesting that EXT1/EXT2 and THSD7A may be associated with autoimmunity." (PMID 39927251, 2025).
diabetes (3 papers, 2013 to 2025). "Despite a limited understanding of EXT2 in metabolism, some studies have associated genetic alterations of EXT2 with an increased risk of diabetes and dysregulated nitric oxide metabolism." (PMID 40234611, 2025).
glioma (3 papers, 2017 to 2026). A benign or malignant brain and spinal cord tumor that arises from glial cells (astrocytes, oligodendrocytes, ependymal cells). "Exostosin glycosyltransferase 1 (EXT1) and exostosin glycosyltransferase 2 (EXT2) catalyze heparan sulfate chain elongation and are increasingly implicated in cancer biology, but their roles in gliomas remain incompletely defined." (PMID 41438585, 2026). "Bulk transcriptomic data from The Cancer Genome Atlas (TCGA) and the Chinese Glioma Genome Atlas (CGGA) revealed that both EXT1 and EXT2 are upregulated in high-grade gliomas and associate with adverse survival, with EXT1 showing the strongest and most consistent prognostic impact." (PMID 41438585, 2026). "To further validate and investigate the functional divergence between EXT1 and EXT2, we performed genome-wide co-expression analyses using TCGA-Glioma transcriptomic data." (PMID 41438585, 2026). "EXT2 expression is enriched in gliomas with pronounced vascular and mesenchymal features, supporting a complementary role in invasive growth and tissue remodeling." (PMID 41438585, 2026). "While both EXT1 and EXT2 were found to be upregulated in gliomas, we prioritized EXT1 for immunohistochemical (IHC) validation due to its stronger transcriptomic association with immune suppression, stromal activation, and clinical outcomes." (PMID 41438585, 2026). "The novelty of this study lies in revealing that EXT1 and EXT2, traditionally viewed as redundant HS polymerases, are in fact spatially partitioned regulators of glioma aggressiveness." (PMID 41438585, 2026). "By aligning multi-omic signals with niche topology, the EXT1 or EXT2 axis model offers a rigorous template for glyco-oncology in glioma and a roadmap for prospective validation in organoids, patient-derived xenografts, and early translational research." (PMID 41438585, 2026). "Among the 33 tumor types analyzed, EXT1 and EXT2 were significantly upregulated in all primary glioma samples relative to normal brain samples, a pattern similarly observed in several other tumor types." (PMID 41438585, 2026). "Given their consistent dysregulation and biological relevance, EXT1 and EXT2 were selected as the principal isoforms for downstream multi-omics analyses in gliomas." (PMID 41438585, 2026). "To further investigate upstream mechanisms driving their dysregulation, we next analyzed the DNA methylation landscapes of EXT1 and EXT2 in TCGA gliomas." (PMID 41438585, 2026). "These insights support the potential of EXT1 and EXT2 as predictive biomarkers and targets for rational drug design in gliomas." (PMID 41438585, 2026). "The study findings identified EXT1 as a central glycosylation-linked regulator of replication stress tolerance and immune remodeling in gliomas, and suggest that EXT2 contributes to extracellular matrix and cytoskeletal reprogramming." (PMID 41438585, 2026). "Here, we performed an integrative multi-omics analysis to dissect the transcriptional, epigenetic, and microenvironmental landscape of EXT1 and EXT2 across gliomas." (PMID 41438585, 2026). "EXT1-high tumors may be vulnerable to synthetic lethality approaches involving checkpoint inhibition (CHK1 or ATR inhibitors), whereas EXT2-driven gliomas might respond to combinatorial regimens targeting cytoskeletal remodeling or focal adhesion dynamics 73-75." (PMID 41438585, 2026). "By contrast, EXT2 preferentially interacted with glypicans and syndecans, reinforcing its involvement in cell adhesion and cytoskeletal remodeling, consistent with its enrichment in mesenchymal-like glioma cells and Ras homology (Rho) guanosine triphosphatase (GTPase)-driven invasive programs." (PMID 41438585, 2026). "We then analyzed the expression patterns of EXT1 and EXT2 across clinical and molecular subtypes in the CGGA glioma patient cohort." (PMID 41438585, 2026).
glioma (continued). "To further elucidate the molecular contexts of EXT1 and EXT2, we constructed PPI networks using STRING based on their top co-expressed genes in gliomas." (PMID 41438585, 2026). "To identify glycosyltransferases relevant to gliomas, we conducted a pan-cancer analysis of EXT family genes (EXT1, EXT2, and EXTL1-3) using harmonized TCGA and GTEx transcriptomic datasets." (PMID 41438585, 2026). "To further characterize the divergent oncogenic roles of EXT1 and EXT2, we performed a GSEA on glioma cohorts stratified by high versus low expression of each gene." (PMID 41438585, 2026).
scoliosis (3 papers, 2021 to 2024). A congenital or acquired spinal deformity characterized by lateral curvature of the spine. "This is the case of EXT2, whose AR inherited disease variants lead to seizures, scoliosis, and macrocephaly syndrome (MIM: 616682), while AD variants cause the multiple exostoses phenotype (MIM: 133701)." (PMID 37858231, 2023). "Interestingly, there is another phenotype associated with the EXT2 gene known as seizure, scoliosis, and macrocephaly/microcephaly (SSM) syndrome, which is caused by biallelic variants in the EXT2 gene." (PMID 40225915, 2024). "For example, EXT2-CDG is associated either with the mono-organ disorder exostoses type 2 (MIM: 133701), affecting only the skeleton, or with a multisystem syndrome (MIM: 616882) characterized by dysmorphia, seizures, scoliosis, and macrocephaly." (PMID 37858231, 2023).
Bone tumors (2 papers, 2021 to 2022). "In this case, palovarotene is directed at benign bone tumors that characterize EXT1/EXT2-CDG, and a trial is being conducted in mice modeling this phenotypic feature." (PMID 35955863, 2022).
breast carcinoma (2 papers, 2022 to 2023). "In another previous paper, EXT2 mutation in breast carcinoma patients was reported." (PMID 36809261, 2023). "EXT2 was downregulated in breast cancer cells but upregulated in squamous cell lung carcinoma." (PMID 35899200, 2022).
colorectal cancer (2 papers, 2023 to 2026). A primary or metastatic malignant neoplasm that affects the colon or rectum. "First, as EXT2/TLA is positively affected by four different clusters, EXT2 presumably plays a central role in the invasive character of colorectal cancer with respect to extracellular matrix (ECM) assembly." (PMID 36672653, 2023).
DEFECT11 syndrome (2 papers, 2011 to 2022). "Data from literature relates PHF21A variants with Potocki-Shaffer Syndrome (PSS), a contiguous gene deletion disorder caused by the haploinsufficiency of PHF21A, ALX4, and EXT2 genes." (PMID 36555772, 2022). "The Potocki-Shaffer syndrome (P11pDs or DEFECT11 syndrome) (OMIM 601224) is caused by deletions in 11p11.2-p12, including the EXT2 and ALX4 genes, and is characterized by patients having MO combined with Foramina Parietalia Permagna (FPP) (OMIM 168500), mental retardation and craniofacial dysotosis." (PMID 21703028, 2011).
glomerulosclerosis (2 papers, 2021 to 2022). A hardening of the kidney glomerulus caused by scarring of the blood vessels. "In membranous lupus nephritis EXT1/EXT2-positive patients have compared to EXT1/EXT2-negative patients more often nephrotic proteinuria, but less glomerulosclerosis and interstitial fibrosis." (PMID 33828546, 2021). "In patients with EXT1/EXT2-positive antigens compared to patients with EXT1/EXT2-negative antigens; nephrotic proteinuria is found more often in patients with membranous lupus nephritis, than in patients with decreasing glomerulosclerosis and renal fibrosis." (PMID 36176440, 2022).
head and neck squamous cell carcinoma (2 papers, 2025 to 2026). A squamous cell carcinoma that arises from any of the following anatomic sites: lip and oral cavity, nasal cavity, paranasal sinuses, pharynx, larynx, and salivary glands. "EXT2 was identified as a prognostic marker in different cancer types such as head and neck squamous cell carcinomas and squamous cell lung carcinoma." (PMID 40234611, 2025).
leiomyosarcoma (2 papers, 2023 to 2024). An uncommon, aggressive malignant smooth muscle neoplasm, usually occurring in post-menopausal women. "In the leiomyosarcoma sample, a bioinformatic analysis of the coding transcriptome data detected an EXT2 gene missense mutation (c.1186G>A) located on exon 7, which was validated by Sanger sequencing." (PMID 36673024, 2023).
lupus nephritis (2 papers, 2021 to 2022). Glomerulonephritis in the context of systemic lupus erythematosus. "The IgG1 dominance for anti-NCAM-1 antibodies shares similarity with anti-EXT1/EXT2 antibodies, supporting the association of both NCAM-1 and EXT1/EXT2 with lupus nephritis." (PMID 33808418, 2021). "Similar to the association of EXT1 and EXT2 with lupus nephritis, NCAM-1 was reported as an antigen for membranous lupus nephritis (MLN) and PMN." (PMID 33808418, 2021). "Approximately 1/3 of patients with class V lupus nephritis are positive for EXT1/EXT2 and the same percentage of mixed class lupus nephropathy (class III/IV with class V)." (PMID 36016931, 2022). "For instance, the EXT1/EXT2-related MN with class V lupus nephritis, MN with undetermined antigen associated with no associated diseases." (PMID 36016931, 2022).
neuroblastoma (2 papers, 2011 to 2022). Neuroblastoma (NB) is the most common solid, extracranial childhood tumor. "In both comparisons the EXT2 seroreactivity was increased in frequency in neuroblastoma patients as compared to Wilms tumor patients." (PMID 22194956, 2011). "Likewise EXT2 was informative for the separation between treated neuroblastoma and treated Wilms tumor patients." (PMID 22194956, 2011). "Furthermore, among the informative antigens was exostosin-2 (EXT2) antigen that was most informative for the separation of untreated neuroblastoma patients from untreated Wilms tumor patients as determined by the AUC value." (PMID 22194956, 2011). "Although these data contribute to understanding the biological role of EXT2, they do not help to understanding the autoantibody response that we frequently found in neuroblastoma." (PMID 22194956, 2011).
Obesity (2 papers, 2009 to 2014). Accumulation of substantial excess body fat. "Interestingly, in a cohort of Pima Indians, who are marked by high levels of insulin resistance and obesity, an association between SNPs in EXT2 and incidence of DM2 was found." (PMID 25541963, 2014). "After we launched this project, other SNPs were identified in obesity or T2D GWAS, including MCR4, TCF7L2 and EXT2, but were not included in our study." (PMID 27990199, 2009).
periodontitis (2 papers, 2019 to 2024). An acute or chronic inflammatory process that affects the tissues that surround and support the teeth. "The heparan sulphate biosynthesis enzymes (EXT1, EXT2, NDST1, and NDST2) displayed comparable correlation with the gingival tissue inflammatory infiltrate in the periodontitis group (EXT1, EXT2 and NDST1 correlated positively, and NDST correlated negatively)." (PMID 38674142, 2024). "Interestingly, HPSE1, EXTs, and NDSTs displayed similar correlation pattern in control and periodontitis group – positive correlations were found for EXT1, EXT2 and NDST1." (PMID 31611818, 2019).
Wilms tumor (2 papers, 2011 to 2022). An embryonal neoplasm characterized by the presence of epithelial, mesenchymal, and blastema components. "MPPED2, ALX4, and EXT2 are associated with WAGR syndrome (Wilms’ tumor, aniridia, genitourinary anomalies, and mental retardation), a developmental disorder." (PMID 36292693, 2022).
achondroplasia (1 paper, 2012). Achondroplasia is the most common form of chondrodysplasia, characterized by rhizomelia, exaggerated lumbar lordosis, brachydactyly, and macrocephaly with frontal bossing and midface hypoplasia. "The EXT1 and EXT2 genes (30 cases) for multiple cartilaginous exostoses, the FBN1 gene for Marfan syndrome (24 cases), and the FGFR3 gene for achondroplasia (22 cases) were most frequently reported in Chinese biomedical literature from the CBM database." (PMID 22913777, 2012).
acute lymphoblastic leukemia (1 paper, 2025). Leukemia with an acute onset, characterized by the presence of lymphoblasts in the bone marrow and the peripheral blood. "The third case, reported in Italy, involved a 14-year-old girl with pre-B acute lymphoblastic leukemia and an EXT2 mutation." (PMID 41441317, 2025).
Burkitt lymphoma (1 paper, 2021). A rare form of malignant mature B-cell non-Hodgkin lymphoma. "Interestingly, these cells lack HS on the cell surface, but exogenous expression of the HS elongation factors EXT1 or EXT2 can restore HS expression in several Burkitt lymphoma cell lines." (PMID 34648606, 2021).
chronic lymphocytic leukemia (1 paper, 2022). "In esophageal carcinoma, however, ODZ4 rearranges with Exostosin Glycosyltransferase 2 (EXT2), while ODZ4 rearranges with Cell Adhesion Molecule 1 (CADM1) and Gram Domain containing 1b (GRAMD1B) in chronic lymphocytic leukemia." (PMID 35011736, 2022).
emphysema (1 paper, 2022). "Palovarotene, a retinoic acid receptor and selective agonist for EXT1/EXT2-CDG, has already shown clinical safety for fibrodysplasia ossificans progressiva and emphysema." (PMID 35955863, 2022).